BDNF (brain derived neurotrophic factor)
Diseases named in the same sentence as BDNF in open-access papers (continued):
Sharing a sentence is not in itself a finding about the gene and the disease.
depression (continued). "The significance of this growth factor is highlighted in studies on patients with major depressive disorder (MDD), in which BDNF is an important regulatory protein in the pathophysiology of the illness." (PMID 39798403, 2025). "BTS ameliorated depression-like behaviors and metabolic dysfunction in HFD-induced obesity through coordinated modulation of inflammation, BDNF signaling, NMDAR expression, and 5-HT neurotransmission in the HPC." (PMID 41244820, 2025). "hsa-miR-16a-5p targets BDNF, NPY4R, and GLUD1, which have been reported to be involved in the pathophysiology of anxiety and depression." (PMID 39821903, 2025). "In study, in addition to lowering the degree of depression, anxiety, stress, and craving, stimulating the DLPFC resulted in a substantial shift in BDNF levels." (PMID 40725591, 2025). "SSRIs have been shown to significantly alleviate depression-like behaviors in animal models of traumatic brain injury (TBI) by increasing serotonin (5-HT) and brain-derived neurotrophic factor (BDNF) in the hippocampus." (PMID 40149758, 2025). "Results showed that the serum BDNF and 5-HT levels of HVS patients in the depression group were significantly decreased." (PMID 41366912, 2025). "LPS from P. gingivalis activates astrocytes and downregulates p75NTR via TLR4, which inhibits the maturation of brain-derived neurotrophic factor (BDNF) and ultimately promotes depression." (PMID 40843171, 2025). "Studies on major depressive disorder have revealed disrupted ERK signaling and decreased BDNF content in the prefrontal cortex and hippocampus." (PMID 39609371, 2025). "In stress-related disorders, including depression, a link among GCs, GR, RACK1 and BDNF has been found." (PMID 39846545, 2025). "To analyze the relationship between the val66met polymorphism of the BDNF gene and depression in Mexican mestizo patients, we separated those subjects with MS who had depression who were considered the cases and the control group from those subjects with MS without depression." (PMID 40003622, 2025). "Electroconvulsive therapy (ECT) increases GMV, particularly in the hippocampal region, enhances BDNF and VEGF expression, and lowers circulating cytokines in patients with depression." (PMID 41303496, 2025). "This study employed a two‐sample Mendelian randomization (MR) approach to investigate the bidirectional relationship between brain‐derived neurotrophic factor (BDNF) and major depressive disorder (MDD), addressing gaps left by prior observational studies." (PMID 40103195, 2025). "For instance, a study has demonstrated that multiple non-coding exons within the brain-derived neurotrophic factor (BDNF) can produce differently spliced transcripts, potentially influencing psychiatric diseases like depression." (PMID 40075226, 2025). "Other markers that are positively correlated with YP include the neuroplasticity marker Brain-Derived Neurotrophic Factor (BDNF) and Gamma-Aminobutyric-Acid (GABA), which is present at low levels in patients with severe depression." (PMID 40440353, 2025). "Ultimately, leptin acts as a neurometabolic signal that links adiposity to BDNF-dependent and NMDAR-dependent synaptic plasticity, in addition to reward processing, mechanisms that are disrupted in depression." (PMID 41375608, 2025). "These include inconsistencies in study designs (e.g., cross-sectional vs. longitudinal), variations in sample characteristics (age, sex, severity of depression, comorbid conditions), and differences in the methods used to measure uPA, tPA, PAI-1, and BDNF." (PMID 40725146, 2025). "Initial studies derived from animal models of conditions such as schizophrenia and depression suggest a deficit in neurotrophic factors like IGF-I and Brain-Derived Neurotrophic Factor (BDNF)." (PMID 40699632, 2025).
depression (continued). "The expression of brain-derived neurotrophic factor (BDNF), synaptophysin (SYN), and postsynaptic density 95 (PSD95) is closely related to the regulation of neuroplasticity, especially synaptic changes in depression." (PMID 39852377, 2025). "Leptin is involved in the neurobiology of depression through several mechanisms, including complex intracellular signalling cascades, NMDAR regulation, modulation of BDNF expression, and brain reward circuitry functioning." (PMID 41375608, 2025). "Therefore, external stimuli may elicit greater responses in them compared to other age groups, explaining why, after exercise and rTMS interventions, adolescents with depression in our study showed a larger increase in serum concentrations of 5-HT and BDNF compared to other studies." (PMID 41477617, 2025). "In depression, studies report low peripheral BDNF levels and higher promoter methylation, while antidepressants and electroconvulsive therapy (ECT) increase BDNF expression and reverse methylation." (PMID 41234420, 2025). "Administration of exogenous H2S significantly improved anxiety and depression-like behavior, mitigated synaptic plasticity deficits, and activated the CREB/BDNF signaling pathway in the hippocampus of adolescent PTSD mice." (PMID 40551819, 2025). "Exploratory analyses in combined groups showed that measures of past drinking, AUD severity, and anxiety/depression positively correlated with IL‐18 and TNF‐α and negatively correlated with BDNF." (PMID 40317574, 2025). "In cortical areas, the picture is less clear, with BDNF in the ACC having facilitatory effects and positive effects on anxiety- and depression-like behaviours, whereas the effects of BDNF in the mPFC are still debated." (PMID 41283278, 2025). "By contrast, n-3 PUFA up-regulated miRNA-182, which correlated with decreased hippocampus brain-derived neurotrophic factor (BDNF) expression, subsequently exacerbating depression-like behaviors." (PMID 41050504, 2025). "In addition, BDNF levels in blood (e.g., serum and plasma) have been extensively examined as a possible biomarker reflecting mental conditions, such as depression, schizophrenia, and Alzheimer’s disease, because measuring BDNF levels in the brains of living humans is difficult." (PMID 40316902, 2025). "A. muciniphila has been shown to elevate BDNF mRNA expression in the HIPP, potentially improving neuronal connectivity and alleviating depression." (PMID 40108902, 2025). "Under conditions of chronic stress, BDNF expression declines markedly in the PFC and hippocampus, leading to synaptic atrophy and behavioral symptoms of depression." (PMID 41179817, 2025). "Furthermore, peripheral plasma levels of neurotrophic factors may not fully capture their dynamic roles in specific brain regions (e.g., amygdala or subgenual ACC), where localized mRNA expression of BDNF-dependent genes could differentially distinguish depression or anhedonia subdomains." (PMID 40365616, 2025). "Genetic studies have also identified several other important genes beyond BDNF and SLC6A4 that influence both epilepsy and depression." (PMID 40941042, 2025). "Meanwhile, the BDNF‐ERK‐CREB pathway was reported to be upregulated by Chai‐Hu‐Shu‐Gan‐San, leading to cognitive improvement and anti‐depression." (PMID 39981856, 2025). "Similarly to MDD, studies have shown significantly decreased BDNF in patients with perinatal depression compared to controls." (PMID 41440970, 2025). "In contrast, other studies show that miR-124a overexpression promotes depression-like behaviors, whereas its inhibition yields antidepressant-like effects, potentially via CREB1 and BDNF upregulation." (PMID 41179817, 2025). "Members of the BDNF signaling pathway such as TrkB, AKT, ERK, and CREB play critical roles in the pathophysiology of depression." (PMID 40371339, 2025).
depression (continued). "This linkage thereby establishes a connection between the BDNF-TrkB-ERK-mTOR1-CREB signaling pathway and the glutamatergic and GABAergic doctrines of depression." (PMID 41340853, 2025). "Resveratrol also shows promise in treating depression, including post-stroke depression, by regulating the HPA axis, reducing inflammation, and enhancing BDNF and neurogenesis." (PMID 40277696, 2025). "For depression, TNF-α interferes with serotonin and dopamine systems by altering how synapses function and reducing levels of brain-derived neurotrophic factor (BDNF), a protein essential for maintaining healthy neurons and stable mood." (PMID 40941042, 2025). "Adult PTSD mice exhibited greater anxiety and depression-like behavior and synaptic plasticity deficits, as well as reduced p-CREB and BDNF compared with adolescent PTSD mice." (PMID 40551819, 2025). "Increased BHB availability enhances H3K9bhb levels on the promoters of Brain-Derived Neurotrophic Factor (BDNF) genes and upregulates their expression, reducing depression and depressive behaviors in mice." (PMID 40675960, 2025). "Several proteins related to neuroplasticity processes have been found to be altered in major depression and animal models of depression, and restored by antidepressant drugs, including mTOR, PSD95, BDNF and synapsin I." (PMID 40405318, 2025). "In the full sample, BDNF was negatively correlated with history of alcohol intake, AUD severity, and depression measures, further implicating these preabstinent group differences as the primary source of group differences in biomarkers." (PMID 40317574, 2025). "In CUMS mice, artemisinin improved depression-like behaviors, upregulated the AKT/GSK/NRF2/HO1 and BDNF/TrkB/ERK/CREB pathways, modulated astrocyte activity, and promoted neurogenesis in the hippocampus." (PMID 41181594, 2025). "It has been shown that dysregulation of the proBDNF/BDNF axis is intricate in the emergence of several neuropsychiatric conditions, including depression." (PMID 40380033, 2025). "Administration of exogenous H2S (one dose for one day) significantly improved anxiety and depression-like behavior and synaptic plasticity deficits, and activated the CREB/BDNF signaling pathway in the hippocampus of adolescence PTSD mice." (PMID 40551819, 2025). "On the other hand, CUMS induction also affects BDNF/TrkB and its downstream PI3K/AKT signaling pathway, resulting in synaptic damage, impaired synaptic plasticity, and ultimately depression." (PMID 41179813, 2025). "Mitochondrial biogenesis and antioxidant defenses are promoted by physical exercise through key signaling pathways, including BDNF, AMPK, PGC-1α, and CaMK, which act to counteract the biochemical and cellular insults of stress and depression." (PMID 40943622, 2025). "Chronic inflammation and disturbances in brain neurotrophic signaling, particularly involving brain-derived neurotrophic factor (BDNF), are thought to be major contributors to this link between CRC and depression." (PMID 40969596, 2025). "In models of depression, 15 Hz rTMS for seven days ameliorated depressive-like behaviors and upregulated hippocampal CB1R, BDNF, and Bcl-2/Bax expression." (PMID 41440017, 2025). "While their direct application in depression remains experimental, their convergence on PGC-1α, BDNF, and mitochondrial pathways underscores potential synergy with exercise in restoring KP homeostasis and reducing the QA/KYNA imbalance observed in MDD." (PMID 41516008, 2025). "The possible underlying mechanisms may partly involve a reduction in oxidative stress and an elevation of BDNF, which in turn enhances functional neuron density in the prefrontal cortex, leading to an improvement in monoaminergic function that results in the alleviation of anxiety and depression." (PMID 39063255, 2024).
depression (continued). "Therefore, it is speculated that a decrease in the activity of the tPA/plasminogen system that is due to a negative effect of plasminogen activator inhibitors may lead to insufficient production of mature BDNF, resulting in the impaired neural plasticity seen in the case of depression." (PMID 39201490, 2024). "Mounting evidence suggests that the decreased expression of the BDNF-TrkB signalling pathway is involved in the pathogenesis of POCD and depression." (PMID 38221533, 2024). "It has been shown that there is increased serum cortisol and miR‐128 and decreased levels of shortened telomeres and BDNF in patients with T2DM and depression." (PMID 37927197, 2024). "Thus, BDNF could be the link between adult hypothyroidism, reduced neurogenesis and depression." (PMID 39100850, 2024). "This treatment activated the BDNF/TrkB/ERK/CREB signaling pathway in the hippocampus of CUMS mice, offering a potential therapeutic approach for depression." (PMID 38389919, 2024). "It is known that the BDNF response to exercise can alleviate mental health disorders, such as depression and anxiety, in animal models and in humans; however, some studies show that ketone bodies might also positively affect brain function through increasing BDNF." (PMID 39338322, 2024). "RES003, a resveratrol derivative with an IC50 of 0.87 μM, can improve chronic stress-induced depression-like behaviors and other psychiatric disorders by inhibiting PDE4 and upregulating the p-CREB/BDNF signaling pathway." (PMID 38968172, 2024). "The study confirmed that A. muciniphila and Amuc_1100 diminish antibiotic-induced anxiety and depression, affecting different parts of the GMBA, including the BDNF/TrkB signaling pathway and astrocyte activation." (PMID 39741949, 2024). "This indicates that both BDNF and TrkB are indispensable components in the VNS mechanism for treating depression, and the BDNF/TrkB signaling pathway plays a crucial role in VNS’s antidepressant effects." (PMID 39734634, 2024). "The findings also showed that vitamin D3 significantly alleviated anxiety- and depression-like behaviors, reduced the expression level of GFAP, and increased BDNF and neuronal protection by inhibiting the overactivation of astrocytes." (PMID 39135986, 2024). "Furthermore, the BDNF pro-peptide was detected in cerebrospinal fluid, and the content was reduced in samples from patients with depression and schizophrenia, indicating that the BDNF research, including our studies, might contribute to the treatment and diagnosis of brain disorders." (PMID 38672461, 2024). "The reduction in E2 weakens the expression of BDNF and PSD-95, affecting synaptic plasticity and leading to emotional disturbances and depression." (PMID 39575307, 2024). "In our sample, in women affected by post-mastectomy pain syndrome, physical activity was found to reduce signs of anxiety and depression, along with a reduction in pain and levels of inflammatory cytokines, corstisol, ACTH, and an increase in BDNF." (PMID 38255692, 2024). "In individuals with depression, one study revealed a correlation between elevated TSH levels, decreased serum BDNF levels, and a lower rise in BDNF during antidepressant treatment." (PMID 38911040, 2024). "By increasing the expression levels of cyclic adenosine monophosphate response-element-binding protein (CREB), protein kinase B, and BDNF in the hippocampus, garlic essential oil demonstrated an antidepressive effect against CUMS-induced depression." (PMID 39459643, 2024). "In preclinical studies of antidepressant effects, baicalein has been found to activate the BDNF/TrkB/CREB signaling pathway and protect against synaptic plasticity damage in mice with depression related to PD." (PMID 39253375, 2024). "While the role of BDNF levels in depression and post traumatic stress disorder (PTSD) has been widely demonstrated, evidence of decreased BDNF in schizophrenic patients is still scarce and needs to be confirmed." (PMID 38275523, 2024).
depression (continued). "BDNF, brain-derived neurotrophic factor; HAM-D, Hamilton Depression Rating Scale; YMRS, Young Mania Rating Scale." (PMID 39493096, 2024). "NMDAR modulators stimulate BDNF expression and exert rapid antidepressant effects, suggesting that NMDAR dysregulation leads to depression." (PMID 39061415, 2024). "BDNF, brain-derived neurotrophic factor; HAM-D, Hamilton Depression Rating Scale; MDD, major depressive disorder; BD, bipolar disorder." (PMID 39493096, 2024). "The objective of this research is to explore the impact of AT1RB therapy on depression and anxiety‐like behaviors triggered by menopause, as well as the levels of NLRP3, IL‐1β, BDNF, and oxidative stress in the hippocampal and prefrontal cortex tissues." (PMID 39443283, 2024). "Compared to the WT-FWT group, the WT-FKO group had a significantly lower level of BDNF and also the display of depressive-like behavior, which indicates that specific microbial taxa changes may mediate the decline in BDNF and thereby promote residual depression-like behaviors." (PMID 38628262, 2024). "In our mouse model of depression induced by lipopolysaccharide, RVG-BDNF-Exos treatment led to a significant increase of BDNF in these key brain regions, crucial for mood regulation and neurogenesis." (PMID 41221079, 2024). "Decreased BDNF levels may reduce the synaptic plasticity of neurons in relevant brain regions, resulting in a decline in cognitive function, weakening of emotional regulation ability, and continuous accumulation of negative emotions, thereby influencing the onset and progression of depression." (PMID 39639753, 2024). "In the FS induced depression mouse model, acupuncture at GV20 and EX-HN3 significantly increased the expression of nerve growth factor (NGF), BDNF, NT-3, and NT-4/5." (PMID 39367470, 2024). "At the end of the experimental procedure, MDA, GSH, BDNF, IL‐1B, and NLRP3 levels were analyzed in the hippocampus to analyze the physiopathological mechanism of menopause‐related depression and the therapeutic effects of valsartan on these mechanisms." (PMID 39443283, 2024). "So, we aimed to evaluate the role of BDNF and CRP in suicidal behavior among Iranian patients with major depressive disorder." (PMID 39039500, 2024). "Blood samples and depression scale scores from elderly patients with depression show that the levels of TNF-α and BDNF are negatively correlated, and the ratio of TNF-α to BDNF is consistent with the Montgomery-Asberg Depression Rating Scale (MADRS)." (PMID 38898454, 2024). "Hesperidin attenuates depression-related symptoms in mice with mild TBI via decreasing neuroinflammation and oxidative damage, and enhancing BDNF production in the hippocampus." (PMID 39327620, 2024). "Additionally, BDNF may serve as a useful biomarker for assessing impaired memory and general cognitive function in aging women, as well as for prenatal hypertensive anxiety and depression in both rats and post-partum women." (PMID 39655343, 2024). "Major Depressive Disorder (MDD) is a neuropsychiatric condition whose neurobiological characteristics include alterations in brain plasticity, modulated by Brain-Derived Neurotrophic Factor (BDNF)." (PMID 39595900, 2024). "Inhibition of the expression of brain-derived neurotrophic factor (BDNF) and nerve growth factor (NGF) in the peripheral nervous system is related to abnormal neural function in the brains of patients with depression." (PMID 39114351, 2024). "In a rat depression model induced by CUMS, ZZCT enhances neuroplasticity through the 14–3–3ζ/GSK-3β/CREB/BDNF signaling pathway." (PMID 39253375, 2024). "Therefore, the trends of BDNF in depression and chronic pain research may be interconnected." (PMID 38617040, 2024).